CD3G (CD3 gamma subunit of T-cell receptor complex)
Diseases named in the same sentence as CD3G in open-access papers (continued):
Sharing a sentence is not in itself a finding about the gene and the disease.
tumor (continued). "Next, we employed lineage-specific markers to annotate clusters into major cell types of the tumor, including T cells (CD3G, CD4, CD8A, CD28, and IL7R), B cells (CD19 and CD20), myeloid cells (HLA-DRA and CD14), fibroblasts (THY1 and ACTA2), and tumor cells (EPCAM and S100A)." (PMID 35634306, 2022). "Moreover, both the CF1 and total TI Treg signatures had superior discrimination ability when compared to previously reported tumor Treg markers, such as FOXP3 and ratio-based signatures CCR8:FOXP3 or CCR8:CD3G 12,13." (PMID 34599187, 2021). "Likewise, immune-related genes such as Cd3g and Il12a appeared altered in a similar manner on the Ats1-KO background, independently of the presence of B16F1 tumours and in line with the increase in T cells observed by flow cytometry." (PMID 30166561, 2018). "A total of 56 molecules are annotated as affecting neoplasia and eight of these are dysregulated over 1.5 fold in Ad12-TC compared to Ad5-TC: down-regulation of ATM, CD19, CD3G, GADD45B, HPSE, TFAP2A and TFPI was observed, whereas levels of EGFR were found to be up-regulated." (PMID 19200380, 2009). "As a common complication of tumor, VTE may be closely related to immune genes CD3G and NR1D2." (PMID 33388092, 2021). "In addition to CYT, we compared the expression of tumor immune response-related genes and found that expression of CD3G gene was significantly higher in 232 Non-Recurrent cases (p = 0.0199) compared to 40 Recurrent cases with statistical significance." (PMID 33476333, 2021). "In our initial analysis, rare non-tumor cells clustered separately from tumor cells, and their identity was further validated by the expression of well-known stromal markers including Vim, Ptprc, Trpm5, Pecam1, Mgp, Cd79a, Itgam, Adgre1, Cd3g, and Marco." (PMID 33821796, 2021). "The expression of T cell cytotoxicity (CD3G, CD3E, CD4, GZMA, PRF1 and TBX21), B cell MHC II and immune exhausted-related genes were abundant in metastatic sites; while MHC I inflammation related genes (HLA-B, HLA-C and IL-1A) were mostly higher in primary than recurrent tumor sites." (PMID 33476333, 2021). "In addition, CD3G+T cells ratio was significantly correlated with CD68 + macrophages, CD4 + T cells, and CD8 +T cells ratio, indicating it could play an important role in the anti-tumor immunity in DLBCL." (PMID 38980810, 2024). "The results showed that CCL17 and CD3G (CD4/CD8+ T cell marker molecule), CD4 (CD4+ T cell marker molecule), and CD79B (naive B-cell marker molecule) were expressed to some extent in tumor tissues of three LUAD patients without dysregulation." (PMID 35321241, 2022). "We could only detect the RNA and protein expression changes of CD3G, but not CD3D, CD3E or CD247 between tumor and normal tissues." (PMID 36176400, 2022).
cancer (17 papers, 2013 to 2025). A tumor composed of atypical neoplastic, often pleomorphic cells that invade other tissues. "Analysis of the TCGA database demonstrated significant associations between CD3D, CD3E, and CD3G expressions and several cancers, including CC (p < 0.05)." (PMID 40702236, 2025). "Prognostic correlations between CD3D, CD3E, and CD3G gene expressions and various cancers were analyzed using the Cancer Genome Atlas (TCGA) database." (PMID 40702236, 2025). "Understanding CD3E and CD3G functions offers insights into therapeutic targeting in immune-related diseases and cancer." (PMID 40621499, 2025). "CD3G is involved in the formation of the TCR-CD3 complex and immune response, and its mutation often leads to diseases such as inflammation and cancer." (PMID 37193034, 2023). "Very few studies mentioned that CD3G was related to the initiation of CESC or the other cancer types." (PMID 36176400, 2022). "During the multi-step process of CESC development, the expression of CD3G was significantly increased starting from CIN1 lesion to cancer." (PMID 36176400, 2022). "The status of miRNAs from the first group which affect the CD3G gene responsible for the CD3-gamma subunit in cancer tissues relative to adjacent normal tissues." (PMID 24244363, 2013). "Interestingly, CD3G can be used as suitable biomarkers to distinguishing cancer in the very early stages of its development." (PMID 30139984, 2018). "Moreover, CD247, CD3G, HLA‐B, HLA‐C, and HLA‐F took part in various pathways, including Th1 and Th2 cell differentiation, PD‐L1 expression and PD‐1 checkpoint pathway in cancer, Th17 cell differentiation, antigen processing presentation, allograft rejection, and cell adhesion molecular." (PMID 35037412, 2022). "Combining NPG with HO-1 inhibitor demonstrated down-regulation of genes involved in cancer cell invasion and proliferation (EGR1, CXCL2, AREG, CXCL3, EREG, CD3e, CD3g, CD74, and B2M) as compared to NPG or to control animals." (PMID 34066839, 2021). "Other drug targets for cancer therapeutics with high CAP scores include MAP4 (60%) and TUBB1 (30%), which are targets of paclitaxel, MAP1A (42%), a target of estramustine, CD3G (39%), a target of muromonab, and PARP1 (37%), a target of olaparib." (PMID 29273096, 2017). "Similarly, genes involved in T cell mediated immune response, such as CD3D, CD3E, CD3G, CD247 in the CD3-TCR complex and downstream effector ZAP70, were more rapidly repressed in LUSC than in LUAD, especially at the early cancer stage." (PMID 27863400, 2017). "miR-378, miR-422a, miR-593 and miR-494 from the first group, which affected the CD3G gene (responsible for the CD3-gamma subunit), and were down-regulated in cancer tissues, when compared to adjacent normal tissues, whereas miR-378 was up-regulated in blood sera of cancer patients." (PMID 24244363, 2013).
infection (12 papers, 2007 to 2025). The state of being infected such as from the introduction of a foreign agent such as serum, vaccine, antigenic substance or organism. "Markers of B cells (Cd19), T cells (Cd3g), and antigen presentation (Cd74 and Cd83) were elevated in aged lungs at day 3 post-infection." (PMID 37852965, 2023). "Taken together, our results indicate that IL-21 was produced by CD3γ/δ+ cells and that IL-21/CD3γ/δ+ cells were markedly upregulated in the anterior, middle and posterior intestine after infection with A. hydrophila." (PMID 37759501, 2023). "Our previous experiments have shown that TCR/CD3 surface receptors are down-modulated after infection with HIV-1 and HIV-2 linked to an initial reduction in CD3γ gene transcripts." (PMID 17822534, 2007). "As the neonate progresses through infection, upregulation of CD3G expression in septic shock may reflect a dysregulated immune response or compensatory overactivation, contributing to cytokine storm and tissue damage." (PMID 40927580, 2025). "In addition, the IL-21-expressing CD3γ/δ T cells were detected in tissues and markedly increased in the anterior, middle and posterior intestine after infection with A. hydrophila." (PMID 37759501, 2023). "It is envisaged that these IL-21-producing CD3γ/δ+ T cells could play important roles in the maintenance of immune homeostasis in fish and the control of excessive inflammation during infections." (PMID 37759501, 2023). "The symptoms are less severe in patients with CD3G mutations, and only two (20%) of all 10 published cases received HSCT due to refractory IBD, AIHA, and granulomatous lymphocytic interstitial lung disease or severe life-threatening infections." (PMID 31921117, 2019). "Previous data from our laboratory showed that CD3 membrane expression was downmodulated after experimental infection of CD4+ T cells with HIV-1, HIV-2, as well as in patients with CD3- CD4+ T-cell lymphoma mediated hypereosinophilic syndrome, all linked to a specific defect in CD3γ gene transcripts." (PMID 17822534, 2007). "After infection, MP antigens stimulate and upregulate T cell surface molecules including CD3D, CD3E, CD3G, and CD8, followed by the upregulation of downstream molecules including CD3Z, FYN, LCK, ZAP70, GADS, P38, and ITK." (PMID 29967623, 2018). "qPCR analysis demonstrated that for genes that were affected either by infection challenge (e.g. AGR2, G6PC, RETNLB) or diet (e.g. IL1R2, CD3G, ADH1C), gene expression levels of the microarray were verified." (PMID 21698235, 2011). "In uninfected and cells immediately post-infection all three DHS sites were open, then the CD3γ promoter became non accessible, and this was followed by a sequential closure of all the DHS sites corresponding to all three transcriptional control regions." (PMID 17822534, 2007). "Infection by HTLV-I has been shown to ultimately downregulate CD3γ, CD3δ, CD3ε, and CD3ζ gene transcripts leading to a CD3- surface phenotype after 200 days of in vitro infection; however, the sequence of gene loss has not been investigated." (PMID 17822534, 2007). "However in contrast to the selective targeting of CD3γ by HIV, HTLV-I infection represses in a sequential manner the expression of all four CD3 genes, a distinction obvious at several stages post-infection." (PMID 17822534, 2007). "Strikingly, we found that the infection with HeV and NiV-B did not modify the expression levels of lymphocyte markers (CD2, CD3D, CD3E, CD3G, CD4, CD8A and CD27) in the lung tissue by 5 dpi." (PMID 29538374, 2018).
bacterial infection (2 papers, 2024 to 2025). "Whereas Class2 uniquely included pathways related to bacterial infections (e.g., E. coli, Salmonella) together with actin-cytoskeleton and T-cell modules (e.g., ACTB, PFN1, RAC2, PIK3CD, CD3D/CD3G, STING1, TRADD, CASP8, BCL2, HLA-F)." (PMID 41394852, 2025).
CD3G also shares sentences with these, for which no sentence is quoted: colorectal cancer (3 papers); head and neck squamous cell carcinoma (3); T-cell lymphoma (3); gastric cancer (2); lung adenocarcinoma (2); atopic eczema (1); autoimmune hypothyroiditis (1); autoimmune lymphoproliferative syndrome (1); B cell deficiency (1); bacteremia (1); bladder cancer (1); blood cancer (1); blood disorders (1); breast invasive carcinoma (1); breast tumors (1); candidiasis (1); chronic granulomatous disease (1); coeliac disease (1); combined immunodeficiency (1); cutaneous malignant melanoma (1); dermatomyositis (1); diarrhoea (1); endocervical adenocarcinoma (1); enteropathy (1); eosinophilia (1); fibrosis (1); Granuloma (1); hypogammaglobulinemia (1); hypothyroidism (1); inflammatory bowel disease (1).
A further 15 diseases each share a sentence with CD3G in 1 paper.